TNF (tumor necrosis factor)
Diseases named in the same sentence as TNF in open-access papers (continued):
Sharing a sentence is not in itself a finding about the gene and the disease.
Insulin resistance (continued). "Inflammatory cytokines such as TNF, IL-6 and MCP-1 have been also shown to inhibit insulin action through modification of signaling properties of insulin receptor substrates, contributing to liver and skeletal muscle insulin resistance." (PMID 21789167, 2011). "In sharp contrast to TNFα negative effects on insulin action, adiponectin positively enhances insulin sensitivity, and hypoadiponectinemia accordingly leads to insulin resistance." (PMID 21941675, 2011). "Although it has been established that anti-TNF therapy improves insulin resistance in RA, it does not seem to reverse rheumatoid cachexia, however it does appear that anti-TNFα therapy halts the progression of muscle deterioration." (PMID 21232112, 2011). "Moreover, in cultured cells, tissues and whole animals, NF-κB has been shown to activate TNFα, IL6, IL-1β, and plasminogen activator inhibitor 1 (PAI-1) inducing insulin resistance." (PMID 20508722, 2010). "The significant role of cytokines, such as TNF-α, IL-6, IL-8, IFN-gamma, IL-1, and IL-17 in the generation of proatheromatous abnormalities (dyslipidemia, insulin resistance, endothelial dysfunction, clotting system activation, and pro-oxidative stress) was reported." (PMID 20706605, 2010). "TNF-α is usually over- expressed in adipose tissues of obese animals and humans, and obese mice lacking TNF-α and/or its receptor demonstrate protection against development of insulin resistance." (PMID 20426802, 2010). "Thus, in the correlation between liver disease and insulin resistance, a link among chronic HCV infection, TNF-α, and T2D possibly exists." (PMID 21994721, 2010). "In particular, the negative effects exerted by TNF on muscle include insulin resistance, downregulation of regenerative pathways and upregulation of protein catabolism." (PMID 19440308, 2009). "When TNF-α wasinfused into healthy humans, we found that TNF-α induces insulin resistance inskeletal muscle, without an effect on endogenous glucose production." (PMID 19148295, 2008). "Hypersecretion of IL-6 and TNFα may exert major stimulatory effects on the synthesis of acute-phase proteins such as PAI-1, which is also related to insulin resistance." (PMID 16787541, 2006). "Overexpression of resistin increased the levels of three proinflammatory cytokines, tumor necrosis factor alpha (TNFα), interleukin 6 (IL-6) and monocyte chemoattractant protein-1 (MCP-1), which play important roles for insulin resistance, glucose and lipid metabolisms during adipogenesis." (PMID 16854242, 2006). "Moreover, excess adipose tissue, especially visceral, is responsible for an increased secretion of adipocytokines, particularly TNFα, which could play a significant role in the development of NASH by exacerbating insulin resistance." (PMID 40727516, 2025). "For instance, it has been shown that TNFα and other cytokines may also activate PTP1B which has been shown to block the IRS1/2‐dependet activation of AKT thereby subsequently leading to the development of insulin resistance." (PMID 39344016, 2025). "Similarly, inflammatory pathways such as TNF, JNK, and suppressor of cytokine signaling (SOCS), which are activated by LPS, aberrantly phosphorylate IRS, leading to reduced insulin signaling and the development of insulin resistance." (PMID 40458405, 2025). "This not only drives the sustained release of pro-inflammatory cytokines (such as IL-1β and TNF-α) but also disrupts insulin signaling through JNK/IRS-1 phosphorylation pathways, forming the pathological basis for chronic low-grade inflammation and insulin resistance." (PMID 40980312, 2025). "However, unlike IL-6, TNF-α can only increase insulin resistance by inhibiting AMPK signaling pathway and decreasing glucose uptake, impairing insulin signaling and lipid metabolism." (PMID 41515940, 2025).
Insulin resistance (continued). "The increased fat mass is responsible for the production of inflammatory markers, such as tumor necrosis factor-alpha (TNF-α), interleukin-6 (IL-6), and other adipokines, which not only exacerbate insulin resistance but also have a direct catabolic effect on muscles." (PMID 40218995, 2025). "TNF-α (tumor necrosis factor-alpha) is a key cytokine that is elevated in both conditions, which is known to inhibit insulin receptor signaling by inducing the serine phosphorylation of insulin receptor substrate-1 (IRS-1), leading to reduced glucose uptake and systemic insulin resistance." (PMID 40142617, 2025). "Existing literature proposes that Yerba Maté polyphenols could potentially modulate hepatic insulin signaling by suppressing TNF-α, and may interact with the PI3K-AKT pathway, involving elements like Akt2 and Irs1, possibly contributing to improved peripheral insulin resistance." (PMID 41244043, 2025). "Key candidates include HOMA-IR to assess insulin resistance, serum testosterone and sex hormone–binding globulin (SHBG) for androgen excess, anti-Müllerian hormone (AMH) to reflect ovarian reserve and follicular activity, and inflammatory cytokines such as TNF-α and IL-6." (PMID 41268159, 2025). "Based on these findings, we hypothesized that macrophage M1 < M2 polarization is related to the EPO-induced renoprotective effects in sucrose-induced insulin resistance model rats and found that EPO decreased the M1 marker TNFα and increased the M2 markers Arg1 and IL10 in the kidney." (PMID 40943240, 2025). "However, we did observe that circulating CRP levels were positively related to body weight, visceral fat mass, and insulin resistance, while IL-6 and TNF-alpha were not related to any metabolic marker." (PMID 40218888, 2025). "In obese PCOS, the altered inflammatory milieu—driven by TNF-α, IL-6, and resistin—can induce the release of EVs enriched with pro-inflammatory microRNAs that disrupt IRS phosphorylation, impede GLUT4 translocation, and modify FOXO1-mediated transcription, thereby exacerbating insulin resistance." (PMID 41010046, 2025). "It is known that MAPKs and NF-κB, activated by tumor necrosis factor-α (TNF-α), reduce insulin signaling, arouse inflammatory responses and interfere with peroxisome proliferator-activated receptor gamma (PPAR-γ) activity, leading to insulin resistance and adipose dysfunction." (PMID 39125686, 2024). "Betulinic acid was also effective at ameliorating TNF-α-induced insulin resistance by preventing the negative regulator of insulin signaling and inflammation-activated protein kinase in adipocytes, thus potentially relieving insulin resistance." (PMID 39063310, 2024). "Furthermore, Fusobacterium can damage the intestinal barrier and result in high expression levels of LPS and TNF-α in patients with NAFLD, which may induce insulin resistance." (PMID 38612992, 2024). "Activated TNF-α can elevate plasma FFA levels by promoting lipolysis, inhibit the tyrosine kinase activity of insulin receptors in muscle tissue, and suppress IRS-1 phosphorylation and GLUT4 gene expression, resulting in insulin resistance and also stimulate IL-6 production." (PMID 40302954, 2024). "Yet, it is not known whether the hypoxia and TNF-α model of insulin resistance and inflammation could be maintained long term in culture." (PMID 39415617, 2024). "The research group hypothesized that mutant RNF213 may lead to insulin resistance independent of TNFα." (PMID 37273690, 2023). "Insulin resistance and hyperglycemia can activate the NLRP3 (NOD (nucleotide oligomerization domain)-, LRR (leucine-rich repeat)-, and PYD (pyrin domain)-containing protein 3) inflammasome, leading to the release of cytokines such as interleukin-1, interleukin-6, and tumor necrosis factor-α." (PMID 37375712, 2023). "Whether TNF-α can act locally, systemically or at both levels, strong evidence clearly establishes that TNF-α overexpression plays a role in the pathophysiology of insulin resistance." (PMID 37514235, 2023).
Insulin resistance (continued). "In addition, TNF-α can inhibit phosphorylation of AMPK Thr172 via the action of protein phosphatase 2C (PP2C), leading to increased levels of free fatty acids and a tendency towards insulin resistance." (PMID 36918975, 2023). "However, we detected no change in global phosphatase activity in the CI, DEX, or TNF models, and changes in the expression of specific phosphatases were limited to chronic models of insulin resistance (CI, DEX, TNF) and not acute models (AA, MPQ)." (PMID 36808134, 2023). "Systemic and ovarian cytokines, such as tumor necrosis factor (TNF)-α, interleukin (IL)-6, and IL-18, can alter the local microenvironment in the ovary, disrupt ovarian function, increase androgen production, and contribute to insulin resistance through various mechanisms." (PMID 38189053, 2023). "This leads to peripheral insulin resistance and impairment of pancreatic β-cell insulin secretion, while the adipocytes elevate adipokine secretion, NGF, interleukin 6 (IL-6), IL-1, tumor necrosis factor-α (TNF-α), and monocyte chemoattractant protein-1 (MCP-1)." (PMID 37373824, 2023). "Furthermore, the anti-inflammatory effects of TPDM6315 on adipocytes stimulated with TNF-α and the induction of GLUT1 and GLUT4 expressions might prevent a progression to insulin resistance." (PMID 37367060, 2023). "We assessed the gene expression of proinflammatory cytokines, such as IL-1β, IL-6 and TNF-α, as well as mTOR and IKKβ in the adipose tissues of the control and experimental rats in order to assess the ability of C. papaya to mitigate HFD-streptozotocin-incited inflammation and insulin resistance." (PMID 36826001, 2023). "In addition, TNF-α induces insulin resistance and lipolysis without affecting fat oxidation, whereas IL-6 has the opposite effect." (PMID 36834025, 2023). "On the other side, serum LPC was decreased by elevated inflammatory status, such as insulin resistance, nonalcoholic steatohepatitis (NASH), and cancer-involved inflammation, where negative correlations were found between LPC and inflammatory markers (CRP and TNF-α)." (PMID 36989310, 2023). "Notably, TNF-α exhibited a dose-dependent effect in inducing insulin resistance, while IL-6 did not contribute to this response." (PMID 37511225, 2023). "Probiotics reduce insulin resistance and oxidative stress by increasing SOD (superoxide dismutase), GSH (glutathione), and catalase (CAT) activity, and reduce the expression of inflammatory cytokine tissue necrosis factor (TNF)-α, interleukin (IL)-1β, and IL-6." (PMID 37374359, 2023). "Nonclassical monocytes also primarily secrete TNF-alpha, a potent inflammatory inducer that can increase insulin resistance and insulinemia by dephosphorylating the insulin receptor substrate (IRS) and AKT via protein-tyrosine phosphatase 1B (PTP1B) activation." (PMID 36979631, 2023). "Thus, it would be important to further investigate whether celecoxib ameliorates hepatic insulin resistance by regulating TNF‐α signalling in a NAFLD mouse model induced by Akt‐driven lipogenesis and characterized by insulin resistance." (PMID 35713152, 2022). "Overproduction of proinflammatory cytokines such as tumor necrosis factor-α (TNF-α), interleukin-1β (IL-1β), and interferon-γ (IFN-γ) in obese animals may be responsible for chronic inflammation and insulin resistance, in part through the nuclear factor kappa-B (NF-κB) pathway." (PMID 35662937, 2022). "These supplements significantly reduced insulin resistance (FBS levels, serum insulin levels (INS), insulin resistance (HOMA‐IR) and HOMA‐B measures), lipid profile (serum cholesterol, VLDL‐cholesterol concentrations, and total cholesterol/HDL levels), inflammation markers (TNF, and IL‐6)." (PMID 35243684, 2022).
Insulin resistance (continued). "Overexpression of SIRT6 in mice provides protection against metabolic pathologies from diet-induced changes, but SIRT6 knockout mice have increased glucose transport and decreased levels of TNF-alpha in the serum which has a negative effect on insulin resistance." (PMID 36225477, 2022). "However, in vivo treatment with this flavonoid prevented weight gain and decreased adipocyte area and the formation of CLS by macrophages around adipocytes, hepatic steatosis and insulin resistance, as well as reduced the mRNA levels of MCP-1 and TNF in the adipose tissue." (PMID 36297370, 2022). "The levels of triglyceride, glucose, insulin, C-reactionprotein (CRP), TNF-α, and total antioxidant capacity (T-AOC) in plasma were increased in OH rats, which were markedly decreased by ADM application in HFD-fed rats, as well as HOMA-IR (homeostasis model assessment of insulin resistance)." (PMID 35745637, 2022). "TNF-α was also reported to be elevated in skeletal muscle tissues, inducing the secretion of IL-6, IL-8, and monocyte chemotactic protein 1 (MCP-1), which may induce insulin resistance." (PMID 35408874, 2022). "TNF-α and IL-1β are pro-inflammatory cytokines and are known to have negative effects on the action of insulin, such as impairing glucose uptake by inhibiting the phosphatidylinositol-3-kinase (PI3K) and protein kinase B (Akt) pathway and promoting the de-elopement of insulin resistance." (PMID 36145139, 2022). "On the other hand, TNF-α may induce lipid overload in the liver, either from de novo lipogenesis through insulin-independent SREBP1 activation, or from excessive lipolysis of WAT elicited by insulin resistance." (PMID 36091076, 2022). "Downregulation of CRP, TNF-α, and nitrites and upregulation of adiponectin could be responsible for LTBI mediated protection against insulin resistance (IR), while the high levels of IL-1β, IL-12, and leptin could be responsible for IR mediated anti-TB immunity." (PMID 35832818, 2022). "Besides, several arachidonic acid metabolites, including PGE2, PGI2, and LXA4, PGE2 and PGI2 can alleviate insulin resistance and improve insulin sensitivity of pancreatic cells; LXA4 can inhibit the production of IL-6, TNF-α, and ROS, thus alleviating inflammation, and has an antidiabetic effect." (PMID 33628839, 2021). "The suppression of TNF-α and JNK signaling pathways and enhancement of glucose uptake and adiponectin secretion could contribute to the protective effects of d-allulose against insulin resistance." (PMID 34684891, 2021). "The anti-inflammatory effects and improvement of insulin resistance in the treatment with Sitagliptin and Berberine-induced synergistic pathways may modulate hepatic transaminases (ALT AST), increase adiponectin, and reduce TNFα." (PMID 34094026, 2021). "Pro-inflammatory cytokines, such as interleukin (IL)-12, IL-6, IL-1β, and tumor necrosis factor (TNF) might play a fundamental role in the onset and progression of NAFLD promoting insulin resistance, oxidative stress, hepatic inflammation, cell necrosis, apoptosis, and liver fibrosis." (PMID 34447378, 2021). "The negative correlation between TNF-α and MMP-2 activity among T2D patients detected here may implicate that increased insulin resistance is associated with reduced MMP-2 activity." (PMID 34821696, 2021). "Therefore, ATF6β could involve in insulin resistance through PI3K-Akt signaling pathway, which also included the role of TNF-α." (PMID 35140684, 2021). "Moreover, this did not hamper our analyses of the effect of anti-TNF on the insulin resistance, as subjects did not receive any treatment and were only used as age and sex-matched controls." (PMID 32776224, 2021). "Other adipokines, such as resistin, seem to be involved in insulin resistance, while tumor necrosis factor alfa (TNF-α) and IL-6, which may be present at early and late stages of NAFLD, increase expression of SREBP-1c in the liver and further promote insulin resistance." (PMID 34950104, 2021).
Insulin resistance (continued). "In addition, the placenta produces TNF-α and leptin, which are highly relevant in GDM pathogenesis since they induce insulin resistance in peripheric tissues and have been proposed as molecules involved in insulin resistance during pregnancy." (PMID 34769262, 2021). "Therefore, circulating TNFα and TNFR2 levels might reflect systemic inflammation which might affect body weight and insulin resistance." (PMID 33441916, 2021). "TNF-α inhibitors are not contraindicated in type 2 diabetes mellitus and/or insulin resistance." (PMID 34829740, 2021). "While both TNF-α and IL-6 could be reduced by CCL4 inhibition, it will be interesting to elucidate whether a broader inhibition of systemic inflammation with a specific chemokine, such as CCL4, could improve insulin resistance in clinical diabetes." (PMID 33968046, 2021). "Besides, data regarding insulin resistance, interleukin 6 (IL-6), tumor necrosis factor-α (TNF-α), and other inflammatory markers were lacking in our study." (PMID 34740348, 2021). "Elevated levels of TNF-α and IL-6 could also trigger the synthesis of C-reactive protein (CRP) in the liver, which is a common systemic inflammatory biomarker and invariably correlates with insulin resistance and the pathogenesis of T2DM." (PMID 34955840, 2021). "Furthermore, TNF-α inhibits AMP-activated protein kinase (AMPK) signaling in muscle and insulin receptor autophosphorylation in fat tissue and the liver, which promotes insulin resistance." (PMID 33807573, 2021). "Moreover, adipocyte-derived factors, such as the increased release of TNFα, IL-6, monocyte chemoattractant protein 1 (MCP-1), and additional products of macrophages, and other cells that populate the adipose tissue are involved in insulin resistance." (PMID 34068151, 2021). "Pro-inflammatory factors, such as leptin, tumor necrosis factor α (TNF-α), monocyte chemoattractant protein 1 (MCP-1), resistin, and FABP4, are elevated, while anti-inflammatory factors, e.g., adiponectin, are low, in chronic systemic inflammation, promoting insulin resistance and atherosclerosis." (PMID 32856199, 2020). "Both TNF-α and SOCS3 may increase insulin resistance via differing possible scenarios." (PMID 31940889, 2020). "One mechanism by which adipose-derived TNFα may promote insulin resistance is by directly activating hormone sensitive lipase (HSL), thereby increasing FFA release from adipocytes which promotes insulin resistance in the liver and skeletal muscle." (PMID 32158768, 2020). "In the heart, chemerin has been shown to induce insulin resistance and apoptosis by decreasing AKT phosphorylation in neonatal rat cardiomyocytes, where chemerin, CMKLR1 mRNA, protein levels, and chemerin secretion are increased by TNFα and decreased by insulin." (PMID 33081064, 2020). "Another is a more indirect scenario by way of TNF-α via stimulating SOCS3 and in turn SOCS3 through affecting the insulin receptor substrate complex leading to the inhibition of the insulin/insulin receptor-mediated pathway, finally resulting in increased adipocyte insulin resistance." (PMID 31940889, 2020). "In addition, increased levels of estrogen, progesterone, and adipocyte-derived hormones such as adiponectin, resistin, tumor necrosis factor alpha (TNFα), interleukin-6 (IL6), and C-reactive protein (CRP) are also suggested to play a role in the development of insulin resistance during pregnancy." (PMID 33114711, 2020). "Moreover, TNF-α could induce serine phosphorylation of IRS-1 and inhibit its triggering of downstream signals, leading to insulin resistance." (PMID 31440472, 2019). "Furthermore, IL-6 inhibits low-grade TNF-alpha-production and may thereby inhibit TNF-alpha-induced insulin resistance and atherosclerosis development." (PMID 31057418, 2019).